STAT3 (signal transducer and activator of transcription 3)
Diseases named in the same sentence as STAT3 in open-access papers (continued):
Sharing a sentence is not in itself a finding about the gene and the disease.
colorectal cancer (continued). "Moreover, loss of KDM4B inhibits the activity of STAT3 to suppress the progression of colorectal cancer, and KDM4B regulates the differentiation of vascular smooth muscle cells into osteoblast-like cells through interacting with STAT3." (PMID 33909202, 2021). "Our study presents evidence on the anti-proliferation and anti-migration effects of EGCG against colorectal-cancer SW480, SW620, and LS411N cells by downregulating the expression of STAT3 and suggests that EGCG could be an effective and natural supplement for colon-cancer treatment." (PMID 33747527, 2021). "It is a small molecule able to abrogate STAT3 signaling, for which it is possible to account 22 different clinical trials (phase I/II and III) in which it is used alone or in combination with other chemotherapeutic agents mainly to treat pancreatic, colorectal cancer and glioblastoma." (PMID 34141616, 2021). "However, other studies have also shown that STAT2 could promote the tumorigenesis of colorectal cancer (CRC) by upregulating the expression of IL-6 and activating the STAT3 signaling pathway." (PMID 34276757, 2021). "Furthermore, knocking down STAT3 in mutant KRAS colorectal cancer cells, but not wild‐type KRAS cells resulted in enhancement of cells’ response to oxaliplatin and 5‐FU." (PMID 33274592, 2021). "While JW-55 showed a negative correlation (−0.655) with STAT3 expression in large intestine cancer, the difference might be owing to the fact that STAT3 expression was varied among different cancer cell lines." (PMID 32486001, 2020). "Examples discussed in this review include Cdc42, Rac1, RhoA, RhoC and RhoH activation of oncogenic STAT3, and in some cases STAT5, in a range of cancers including but not limited to: breast, bladder, gastric, cervical, myeloid, pancreatic, hepatocellular, head and neck, and colorectal cancer." (PMID 32915198, 2020). "Interestingly, and in agreement with previous work, we found that the expression of STAT3 was not affected in HCT116 colorectal cancer cells after carnosol treatment." (PMID 31456939, 2019). "Thus, our study indicates that the high level of IL-35 in colorectal cancer promotes the production of IL-35 via STAT1 and STAT3, which suppresses T cell proliferation and may participate in tumor immunotolerance." (PMID 27682874, 2016). "Similar results were observed with a combination of MEK and STAT3 inhibitors in K-Ras mutant HCT-116 and LS174T colorectal cancer cells, which further support the hypothesis that inhibiting dual MEK and STAT3 pathways in K-Ras mutant cells can increase sensitivity to MEK inhibitors." (PMID 25961376, 2015). "Several studies have reported that the STAT3 signaling pathway influenced tumor angiogenesis, infiltration and metastasis by regulating the expression of VEGF, MMPs or bFGF in pancreatic cancer, colorectal cancer, gastric cancer, HCC and several other types of tumors." (PMID 24944688, 2014). "Therefore, miR-27a could be a useful biomarker for monitoring colorectal cancer development and progression, and also could have a therapeutic potential by targeting SGPP1, Smad2 and STAT3 for colorectal cancer therapy." (PMID 25166914, 2014). "Moreover, colorectal cancer cell growth and progression are promoted by CAF-derived IL-6; a vicious circle of colorectal cancer growth and progression is formed when IL-6 from CAFs induces STAT3 activation, which promotes the production of autocrine IL-6 in CAFs." (PMID 36635302, 2023). "Furthermore, the present results showed that in DU-145 cells, IL-6 may be involved in activation of STAT-3 in an autocrine manner; IL-6 is higher in tumoral compared with non-tumorigenic tissue, in patients with breast and colorectal cancer and PCa." (PMID 35703345, 2022). "Previous reports showed that p-STAT3 and β-Catenin could not directly interact, while inhibition of STAT3 resulted in the loss of β-Catenin in the nucleus and reduction of β-Catenin/TCF transcription in colorectal cancer." (PMID 24312384, 2013).
colorectal cancer (continued). "The 3- and 5-year survival rates of STAT3 protein-positive colorectal cancer patients were lower than the rates in STAT3 protein-negative patients, indicating that STAT3 may play a role in tumorigenesis, is related to the degree of malignancy, and influences the prognosis of colorectal cancer." (PMID 23170117, 2012). "In colorectal cancer, tumor-infiltrated macrophages secreted CCL5, which activates p65/STAT3 pathway and indirectly stabilizes PD-L1 protein rather than increasing the mRNA expression of PD-L1 in cancer cells." (PMID 34771505, 2021). "The formation of colorectal cancer stem-like tumorspheres was inhibited by BBI608, a STAT3 inhibitor, but not by regorafenib." (PMID 33023006, 2020). "We found that PRSS8 inhibited Sphk1/S1P/Stat3 signaling, in terms of negative correlation of PRSS8 and Sphk1 in vitro, in Sphk1 mouse model and in human colorectal cancers." (PMID 27050145, 2016). "Recently, we discovered that STAT3 suppresses epithelial-to-mesenchymal transition (EMT) and thus metastasis in a mouse model of colorectal cancer (CRC), while it did not affect the overall tumor burden." (PMID 24995503, 2014). "We observed that GO-Y030 inhibited STAT3 phosphorylation (Y705), but not ERK1/2 phosphorylation (T202/Y204) in the ALDH+/CD133+ subpopulation of SW480, HCT-116, DLD-1, and HT29 colorectal cancer cell lines." (PMID 21694723, 2011). "We found FLLL32 effectively decreased the levels of phosphorylated STAT3 (P-STAT3, Y705) in SW480 and HCT116 colorectal cancer cells and curcumin is not as potent as FLLL32." (PMID 20712901, 2010). "The relationship between the overexpression of p-STAT3 and other clinicopathological parameters (including TNM stage, tumor differentiation, and gender) was not statistically significant by random effects model in colorectal cancer patients." (PMID 27504822, 2016). "Clinical stage, postoperative chemotherapy, VEGF-C protein expression and histological grade were independent prognostic factors in colorectal cancer, while presence of residual tumor after surgery and PTEN and STAT3 protein expression were not independent prognostic factors." (PMID 23170117, 2012). "Opioid-induced STAT3 activation without any concomitant effect on the WNT/β-Catenin pathway was surprising, as ABC/WNT signaling is considered an essential driver of cell motility and it synergizes in colorectal carcinoma progression with oncogenic STAT3 activation." (PMID 33465556, 2021).
gastric cancer (797 papers, 2004 to 2026). A primary or metastatic malignant neoplasm involving the stomach. "Overexpression of STAT3 is associated with poor prognosis in hepatic, breast, thyroid, and gastric cancers." (PMID 40303286, 2025). "In gastric cancer, elevated levels of phosphorylated STAT3 (pY705 STAT3) have been associated with reduced overall survival." (PMID 40166646, 2025). "GRIM-19 is a component of mitochondrial complex I and STAT3 signaling, and its alterations in human gastric cancer are associated with mitochondrial dysfunction and enhanced inflammatory signaling." (PMID 40673273, 2025). "Numerous studies have reported the constitutive activation of STAT3 in gastric cancers as well as its tight association with the prognosis and clinicopathological characteristics of gastric cancer patients." (PMID 38273295, 2024). "Retrospective clinical data revealed that high levels of IL-6, p-Stat3, and PD-L1 are associated with a decrease in the integrity of the gastric cancer environment, which is correlated with suboptimal patient survival rates." (PMID 39309860, 2024). "A similar effect was observed in gastric cancer cells treated with the STAT3 inhibitor W1131 caused by reduced STAT3 occupancy on the GPX4, SLC7A11, and FTH1 promoters." (PMID 38539832, 2024). "Kai-Wen Hsu reported that the levels of expression of Notch1 and Jagged1 are strongly associated with the levels of phosphorylated STAT3 and Twist in gastric cancer tissues." (PMID 39309860, 2024). "Cripto-1 and STAT3 are implicated in the formation and expansion of the gastric cancer stem cell population, with concurrent increases in p63 protein activity noted." (PMID 39309860, 2024). "Aberrant activation of the STAT3 pathway has been implicated in the initiation, progression, and therapeutic resistance of several cancers, with gastric cancer being particularly affected." (PMID 39309860, 2024). "Considerable evidence demonstrates that the JAK/STAT3 pathway is the primary signaling pathway upregulated to induce cancer-associated fibroblast (CAF) cells in gastric cancer resulting in the proliferation and metastasis of cancer cells." (PMID 39507759, 2024). "This article highlights the role of STAT3 as an important transcription factor that plays a key role in various cellular functions associated with gastric cancer." (PMID 39309860, 2024). "In gastric cancer, associated MSCs prime neutrophils through the secretion of IL-6 and activate neutrophil STAT3 and ERR1/2 pathways, and in turn, neutrophils induce differentiation of normal MSCs into CAFs." (PMID 37046676, 2023). "In summary, despite the reported role of STAT3 in numerous cancers, its anti-gastric cancer effects and the underlying molecular mechanisms involving PA have not been established." (PMID 36672337, 2023). "IL-22 produced by cancer-associated fibroblasts has been reported to promote gastric cancer cell invasion via STAT3 and ERK signaling." (PMID 36977736, 2023). "The latest study suggests that Signal transducer and activator of Transcription 3 (STAT3)-mediated ferroptosis is associated with chemoresistance in gastric cancer." (PMID 36105219, 2022). "Higher STAT3 and STAT3 phosphorylation from persistent activation was associated with an unfavorable prognosis in gastric cancer." (PMID 35892729, 2022). "Collectively, our results provide a molecular framework by which miR-21 mediates inflammation-associated gastric cancer progression, and establish miR-21 as a robust therapeutic target for solid malignancies characterized by excessive Stat3 activity." (PMID 35053428, 2022). "5-fluorouracil in combination with berberine or curcumin caused a synergistic inhibition of STAT3 and survivin level, resulting in enhanced cell death in gastric cancer cells." (PMID 36144625, 2022). "Accordingly, increased Stat3 activity is also associated with lymph node metastasis and an overall poor prognosis in gastric cancer patients." (PMID 35053428, 2022).
gastric cancer (continued). "Chronic stress causes the upregulation of NF-κB, CREB and STAT3, leading to gastric cancer (GC) cell proliferation and metastasis by inducing the release of NE and its binding to β-AR." (PMID 34988010, 2021). "Herein, hyperactivation of STAT-3 has been associated with enhanced EZH2 expression resulting in a poor prognosis of multiple cancers types like gastric carcinoma." (PMID 35127527, 2021). "It has been well documented that H. pylori infection causes activation of STAT3 which is implicated in gastric cancer initiation and progression." (PMID 32973302, 2020). "NC inactivated the signal transducers and activators of transcription 3 (STAT3) signaling pathway and caused attenuation of cell proliferation and angiogenesis in gastric cancer." (PMID 33288736, 2020). "IL-6 expression is markedly associated with STAT3 and enhances the invasion of gastric cancer cells 48,49." (PMID 31892988, 2020). "Another important inflammatory regulator, STAT3, greatly promotes tumor growth and is referred to as a hallmark of gastric cancer." (PMID 33144870, 2020). "STAT3 signaling has been linked to severe gastric pathology during H. pylori infection as well as to gastric cancer development." (PMID 31065023, 2019). "Recent results revealed that the long non-coding RNA (lncRNA) PVT1 (long non-coding RNA encoded by the human PVT1 gene) binds STAT3 and protects it from ubiquitin-dependent degradation in gastric cancer." (PMID 31557897, 2019). "A recent meta-analysis has clearly shown that elevated p-STAT3 activity is not only significantly associated with poor prognosis of stomach cancer patients, but with undifferentiated type and lymph node metastasis." (PMID 30202514, 2018). "Methylation of STAT3 can influence relevant traits through altering gene activity, leading to consequences such as increasing the risk of gastric cancer." (PMID 29596388, 2018). "Here, we observed tumour‐associated TLSs in a preclinical mouse model (gp130F/F) of gastric cancer, where tumourigenesis is dependent on hyperactive STAT3 signalling through the common IL‐6 family signalling receptor, gp130." (PMID 29417587, 2018). "Several studies have suggested the crucial role of STAT3 in gastric cancer cell survival, such that loss of STAT3 led to cell cycle arrest in the G1 phase." (PMID 29383166, 2017). "We postulate that SIRT1 and STAT3 are potential early diagnostic and prognostic markers of gastric cancer." (PMID 28061480, 2017). "Other potential growth-promoting signals are the abundant pro-inflammatory cytokines present in this model, which have been previously linked to gastric cancer development in humans and are reflected in the widespread activation of STAT3 in tumor epithelia." (PMID 26859571, 2016). "Our research has demonstrated that the increased p-STAT3 expression not only predicts poor prognosis of gastric carcinoma patients, but is also associated with worse tumor differentiation and lymph node metastasis in patients with gastric carcinoma." (PMID 27504822, 2016). "Among the tumor types evaluated, gastric cancer was the tumor type most linked with a worse outcome for patients who expressed high level of p-STAT3 (HR = 2.264, 95% CI: 1.629–3.147, P<0.001, I2 = 52.2%)." (PMID 26024373, 2015). "Harbouring STAT3 polymorphism plus infection with CagA strains possessing higher number of EPIYA-C segments was more strongly associated with gastric cancer." (PMID 26186918, 2015). "It has been also showed that activation of STAT3 pathway is associated with progression to gastric cancer." (PMID 25594045, 2014). "In the present study, a case-control study was conducted in which rs2293152 and rs744166 polymorphisms in STAT3 were analyzed in 209 Chinese patients with gastric cancer and 294 cancer-free controls." (PMID 24864251, 2014). "In the context of Helicobacter pylori-associated gastric cancer, the existence of a positive feedback loop between STAT3 and COX-2 was also demonstrated." (PMID 24995504, 2014).
gastric cancer (continued). "The aim of this study was to explore the association between polymorphisms in signal transducer and activator of transcription protein 3 (STAT3) and the risk of gastric cancer." (PMID 24864251, 2014). "Impaired tumor development in IL-6−/− mice was correlated with the decreased activation of STAT3, a factor associated with gastric cancer cell proliferation." (PMID 23593346, 2013). "In the present study, we investigated the association of interleukin (IL)-6/STAT3 signaling pathway with T lymphocytes and clinical implication in patients with gastric cancer." (PMID 24116074, 2013). "This is consistent with our findings that IL-6 expression was markedly associated with STAT3, and they were both over-expressed in human gastric cancer." (PMID 24116074, 2013). "Infection with H.pylori, which is closely associated with gastric cancer, also activates STAT3 through its cytotoxin-associated gene A." (PMID 23658720, 2013). "This gp130Y757F mutation impairs SOCS3-mediated negative feedback regulation, leading to hyperactivation of the IL-6/JAK/STAT3 pathway, which is one of the most frequently dysregulated signaling cascades in human gastric cancer and is associated with inflammation, proliferation, and immune evasion." (PMID 40673273, 2025). "Targeting the STAT3 pathway and its associated noncoding RNAs may hold promise for improving treatment outcomes in gastric cancer and other gastrointestinal malignancies." (PMID 40860906, 2025). "The current investigation concentrated on the molecular mechanisms associated in the JAK/STAT3 pathways, which might suggest repression in the initial stages of gastric cancer progression." (PMID 40350446, 2025). "In the current study, we sought to establish whether Yap1 activity was intrinsically associated with that of gp130/Stat3 signalling-dependent carcinogenesis and to clarify the underlying mechanisms that control gastric cancer initiation and development." (PMID 37957015, 2024). "IL-6 can activate the STAT3 pathway, which is associated with gastritis and gastric cancer." (PMID 38978704, 2024). "The data suggested that GDF15 expression is associated with STAT3 expression in gastric cancer." (PMID 36769245, 2023). "In this scenario, the role of the IL-6/STAT3 pathway may represent a target for innovative gastric cancer therapeutic strategies often associated with clinically aggressive features and resistance to conventional therapy." (PMID 36979673, 2023). "Furthermore, to determine the association between GDF15 and STAT3 in gastric cancer, we analyzed their correlation in the GEPIA dataset." (PMID 36769245, 2023). "Furthermore, RhoC activation of STAT3 has been recently implicated in gastric cancer, with elevated RhoC and pTyr705 STAT3 observed in tumour samples." (PMID 32915198, 2020). "However, in contrast to the co-activation of AKT and STAT3 signaling in PIK3R1 loss ovarian cancer cells, the molecular rationale underlying the synergism in the KRAS mutant gastric cancer cells is the activation of STAT3 upon inhibition of PI3K signaling." (PMID 30755611, 2019). "Others have found that hsa-miR-18a-5p targets PIAS3 directly and in this way causes an increase in STAT3 transcriptional activity in gastric cancer cell lines fitting with the hypothesis for hsa-miR-637." (PMID 31063487, 2019). "We also show frequent loss of TFF1 with nuclear localization of STAT3 in human gastric cancers." (PMID 31292446, 2019). "Constitutive activation of STAT3 is closely associated with chemoresistance in gastric cancer." (PMID 29409467, 2018). "Thus, the anti-neoplastic effect of GHRH antagonist, MIA-602, was found to be associated with blockage of GHRH-R-mediated PAK1/STAT3/NF-κB pathways in gastric cancers." (PMID 29983893, 2018). "Aberrant STAT3 activation occurs in most human gastric cancers (GCs) and contributes to the malignant progression of GC, but mechanism(s) underlying aberrant STAT3 remain largely unknown." (PMID 27167343, 2016).